MAFB (MAF bZIP transcription factor B)
Description:
Acts as a transcriptional activator or repressor. Plays a pivotal role in regulating lineage-specific hematopoiesis by repressing ETS1-mediated transcription of erythroid-specific genes in myeloid cells. Required for monocytic, macrophage, osteoclast, podocyte and islet beta cell differentiation. Involved in renal tubule survival and F4/80 maturation. Activates the insulin and glucagon promoters. Together with PAX6, transactivates weakly the glucagon gene promoter through the G1 element. SUMO modification controls its transcriptional activity and ability to specify macrophage fate. Binds element G1 on the glucagon promoter (By similarity). Involved either as an oncogene or as a tumor suppressor, depending on the cell context. Required for the transcriptional activation of HOXB3 in the rhombomere r5 in the hindbrain (By similarity).
Synonyms: KRML; DURS3; MCTO
Tractability: PROTAC: UniProt records ubiquitination sites on it; ubiquitination databases record sites on it.
Gene: Protein-coding gene on chromosome 20 (40,685,848 to 40,689,236, reverse strand). Ensembl gene ENSG00000204103.
Subcellular location: Nucleus
Subcellular location (Human Protein Atlas): Nucleoplasm; Cytosol; Golgi apparatus; Nucleoli
Pathways (Reactome):
Developmental Biology: Activation of anterior HOX genes in hindbrain development during early embryogenesis
Gene Ontology:
Molecular function: identical protein binding; protein binding; DNA-binding transcription factor activity, RNA polymerase II-specific; RNA polymerase II cis-regulatory region sequence-specific DNA binding; sequence-specific DNA binding; DNA binding; DNA-binding transcription activator activity, RNA polymerase II-specific; DNA-binding transcription factor activity; protein-containing complex binding; sequence-specific double-stranded DNA binding
Biological process: negative regulation of erythrocyte differentiation; regulation of DNA-templated transcription; abducens nerve formation; fat cell differentiation; integrated stress response signaling; negative regulation of osteoclast differentiation; negative regulation of transcription by RNA polymerase II; positive regulation of DNA-templated transcription; regulation of myeloid cell differentiation; regulation of transcription by RNA polymerase II; sensory organ development; cornified envelope assembly; gene expression; keratinocyte differentiation; positive regulation of transcription by RNA polymerase II; protein processing
Cellular component: nucleus; RNA polymerase II transcription regulator complex; chromatin; transcription regulator complex
Genetic constraint (gnomAD): Loss-of-function variants: 3 observed, 16.54 expected, observed/expected ratio (o/e) 0.18, 90% interval 0.082 to 0.47. The upper end of that interval is the gene's LOEUF score, 0.47, which puts it in group 2 of 6, group 1 being the genes least tolerant of losing a copy. Missense variants: 355 observed, 438.02 expected, observed/expected ratio (o/e) 0.81, 90% interval 0.74 to 0.88. Synonymous variants: 214 observed, 208.01 expected, observed/expected ratio (o/e) 1.03, 90% interval 0.92 to 1.15.
Homologues: Orthologues: macaque MAFB (100% identical), chimpanzee MAFB (99% identical), pig MAFB (99% identical), dog MAFB (98% identical), guinea pig MAFB (98% identical), rat Mafb (98% identical), mouse Mafb (97% identical), tropical clawed frog mafb (76% identical), rabbit MAFB (74% identical), zebrafish mafba (71% identical), Drosophila melanogaster tj (37% identical), Caenorhabditis elegans maf-1 (16% identical), and 1 more. Paralogues in human: MAF (60% identical), MAFA (59% identical), NRL (39% identical), MAFK (22% identical), MAFG (20% identical), MAFF (19% identical).
Diseases named in the same sentence as MAFB in open-access papers:
MAFB is named in the same sentence as 127 diseases in open-access papers, as found by Europe PMC text mining. Sharing a sentence is not in itself a finding about the gene and the disease. The quoted sentences say what the papers report.
multiple myeloma (23 papers, 2007 to 2025). "APOBEC signature is associated with MAF and MAFB translocations in multiple myeloma, and such translocations are markers of poor prognosis." (PMID 32471990, 2020). "MAFB aberrations often lead to disease; chromosomal translocations result in ectopic MAFB expression in human myeloma cells, domain-specific MAFB mutations cause multicentric carpotarsal osteolysis syndrome, and elevated MAFB expression was observed in acute myeloid leukemia blasts." (PMID 27829226, 2016). "In particular, aberrant MAFB activity has been associated with the progression of diseases such as multiple myeloma and acute myeloid leukemia as well as other solid tumors, where it may contribute to the survival and proliferation of malignant cells, thereby promoting disease progression." (PMID 40506426, 2025). "Mutation of at least one out of five genes (cyclin D1, C-MAF, FGFR3/MMSET, cyclin D3 and MAFB) seems to be a consistent finding in plasma cell myeloma which requires about three such rate limiting steps on average to manifest clinically." (PMID 40720480, 2025). "MAFB was reported as an oncogene involved in inducing multiple myeloma, and Human Protein Atlas (HPA) data indicate that the expression of MAFB is related to the growth of endometrial cancer." (PMID 36012611, 2022). "Taken together, these results suggest that myeloma cells with high MAFb protein due to translocation to 20q11 or Igλ, or insertion on 20q11 are associated with resistance to proteasome inhibitors." (PMID 29980194, 2018). "Chromosome translocation in multiple myeloma results in aberrant MAFB expression, and miR-223 suppresses nasopharyngeal carcinoma cell proliferation and migration by targeting MAFB." (PMID 27829226, 2016). "MAFB plays important roles in the development and differentiation of various organs, tissues and cells, and MAFB dysregulation has been identified in multiple myeloma and other tumors." (PMID 27829226, 2016). "In multiple myeloma, MAFB can make hematopoietic stem/progenitor cells reprogramed into malignant plasma cells." (PMID 26055874, 2015). "Induced gene expression in stimulated TCam-2 cells: MAFB induces differentiation, coexistently it is known as oncogene in multiple myeloma." (PMID 23969837, 2013). "Interestingly, hypoxic stimulation increased MAFB/MafB expression in myeloma cells; in addition, the knockdown of MAFB under hypoxic conditions suppressed HMOX1 expression." (PMID 36775962, 2023). "We found that even in the absence of translocation, hypoxic stress increased the expression of MAFB/MafB, which is a poor prognostic factor in myeloma, and that MAFB may be involved in HMOX1 expression." (PMID 36775962, 2023). "In myeloma, overexpression of MAFb in U266 cells also enhances proliferation." (PMID 29980194, 2018). "In addition, MAFB is expected to be highly sensitive and very specific biomarker for poor prognosis of multiple myeloma patients." (PMID 26055874, 2015). "Increased MAFB gene expression has been observed in myeloma." (PMID 17389914, 2007). "The protein expression of MAF, MAFB, and ARK5 was analyzed in nine human myeloma cell lines: Sachi, KM5, L363, JJN3, KMS-11, RPMI-8226, FR4, NOP-1, and KMS-12." (PMID 38282096, 2024). "In particular, in 8–10% of multiple myelomas the MAF, MAFB, and MAFA genes are translocated to the immunoglobulin heavy chain locus." (PMID 35406570, 2022). "Among the stable myeloma precursor condition cases, we identified only 11 SV hotspots: all translocations between the IGH locus and CCND1 (n = 7), MAFB (n = 2), CCND3 (n = 1), and LTBR|LAG3 (n = 1)." (PMID 33767199, 2021). "The microarray data also pointed to a significant upregulation of two primary MAFB target genes, i.e., RND3 and MYO5A, which were known to be upregulated in multiple myeloma plasma cells." (PMID 32178359, 2020).
multiple myeloma (continued). "MAF transcription factors were originally identified as oncogenes and chromosomal translocation events in multiple myelomas frequently lead to the over-expression of c-MAF and MAFB." (PMID 19303416, 2009). "Multiple myeloma is an incurable plasma cell malignancy, which is characterized by recurrent chromosomal aberrations that drive the expression of established oncogenes such as MYC, Cyclin D1, FGFR3/MMSET and MAF/MAFB." (PMID 33494394, 2021). "The data also rules out abnormalities involving MAF, MAFB, MYC or NSD2/FGFR3, which are chromosomal translocations clinically relevant for multiple myeloma diagnosis." (PMID 40027317, 2024).
diabetes (15 papers, 2015 to 2023). "We also showed that the human β-cell-specific gene DLK1 was significantly positively correlated with both MAFA and MAFB which had also been implicated in the progression of diabetes by impairing β-cell function." (PMID 30567413, 2018). "MAFB also has been linked to the metabolism and development of obesity and diabetes." (PMID 32831068, 2020). "In addition, this gene has been related to serum lipid concentrations, and also, the ischemic heart disease and stroke risk, which means that MAFB gene interacts with higher BMI, hypertension, and diabetes." (PMID 31387249, 2019). "Notably, the decrease of insulin+MafA+ cells and the increase of insulin+MafB+ cells preceded the onset of diabetes, consistent with a causative role in hyperglycaemia, rather than a consequence thereof." (PMID 28598424, 2017). "Loss of MAFB in early T2D may promote β cell reprogramming; thus, understanding the stepwise transitions toward dysfunction, which are potentially reversible, may facilitate the production of therapies in which early β cell dysfunction can be targeted to slow the progression to overt diabetes." (PMID 37606041, 2023). "Following previous results, the present study uses a previously-generated diabetes mellitus murine model of Pdx1-dependent, Mafb-deletion mice under Mafa knockout conditions (A0BΔpanc) to detect the possible mechanisms of MafB function under pathological conditions in adult mice." (PMID 35862726, 2022). "It is well known that diabetes was independently risk factor for incidence of CAD and IS, and it may interact with the SNP of rs2902940 in the MAFB to favor the incidence of CAD and IS." (PMID 26204962, 2015). "Similarly, the abundance level of MAFB was lower in human islets, indicating that S7 cells, regardless of the mutation or diabetes status, are less mature than human islet cells (orange background)." (PMID 28684784, 2017). "Interestingly, there are no reported associations between MAFB and diabetes susceptibility." (PMID 32488111, 2020). "Taken together, the data show that reduced expression of MafB in human islets may impede the proliferation of β cells that is normally triggered by increased metabolic stress and stimulate apoptosis, as we demonstrate in this paper, leading to diabetes mellitus." (PMID 31208980, 2019). "In this manuscript, we investigated expression patterns of 3 TFs with known changes in islet cell development and diabetes: α cell–specific ARX, β cell–specific MAFA, and MAFB, which is expressed in both α and β cells and has a unique expression profile compared with rodent islets." (PMID 34428183, 2021).
atherosclerosis (9 papers, 2015 to 2024). A disease characterized by the build-up of fatty material and calcium deposition in the arterial wall resulting in partial or complete occlusion of the arterial lumen. "Transcription factor MafB regulates differentiation and activity of monocytes/macrophage and is associated with the development of atherosclerosis and cancers." (PMID 31447817, 2019). "MAFB gene polymorphisms are associated with lipid levels, coronary disease, and atherosclerosis." (PMID 35860693, 2022). "MAFB has been reported to promote atherosclerosis by inhibiting apoptosis of foam-cells in a mouse model." (PMID 36406405, 2022). "In this stage, MafB was reported to play atherosclerosis promoting roles by up-regulating apoptosis inhibitor of macrophages (AIM) and thereby suppressing apoptosis of macrophage foam-cells." (PMID 28790455, 2017). "MafB, a transcription factor expressed selectively in macrophages, has important roles in some macrophage‐related diseases, especially in atherosclerosis." (PMID 27419056, 2016). "We have previously demonstrated that MafB directly regulates AIM expression in foam cells in atherosclerosis." (PMID 27419056, 2016). "As the AIM promoter region contains a MARE and MafB binds to this site in macrophage within atherosclerosis lesion 9, it is possible that MafB directly regulates AIM expression in ATMs." (PMID 27419056, 2016). "In an earlier study, MAFB was found to promote hyperlipidemic atherosclerosis by suppressing foam-cell apoptosis." (PMID 26204962, 2015). "Together, the effects of MAFB gene on lipid metabolism and atherosclerosis are complex and multiple channels needed further research." (PMID 26204962, 2015). "Recent studies showed that MAFB was involved in macrophage apoptosis, which was important in the development of atherosclerosis, suggesting a role of MAFB in the disease." (PMID 26204962, 2015). "First, due to enhanced expression of PU.1, KLF4, MafB, and LXRα, these cells acquired antiinflammatory properties, including the increased secretion of IL-10, IL-1RA, and IL-5, aiding to resolve inflammation and protect against atherosclerosis." (PMID 39531328, 2024). "Further, we examined whether MafB plays a physiological functional role in regulating macrophage cholesterol efflux and thus the development of atherosclerosis." (PMID 28790455, 2017). "Our previous study showed that MafB promotes atherosclerosis by regulating AIM expression." (PMID 29167450, 2017). "Especially, LXR regulates AIM through MafB regulation in macrophage within atherosclerosis lesion." (PMID 27419056, 2016). "Our findings should be important to help clarifying the role of MAFB in atherosclerosis." (PMID 26204962, 2015). "The v-maf avian musculoaponeurotic fibrosarcoma oncogene homolog B gene (MAFB) has been associated with serum lipid levels in the Eurpean population, but little is known about such association in the Chinese population or in atherosclerosis-related patients." (PMID 26204962, 2015). "The present study showed that the nuclear receptor-MafB-C1q pathway was macrophage-specific, which may facilitate the development of drugs for macrophage-related pathologies, such as autoimmune disease and atherosclerosis." (PMID 29167450, 2017). "Collectively, these findings support the view that MafB may be broadly targeted by pro-inflammatory and pro-atherogenic microRNAs, and the resulting deterioration of protective MafB activities in turn may increase host vulnerability to the development of atherosclerosis." (PMID 28790455, 2017).
COVID-19 (9 papers, 2020 to 2025). A disease caused by infection with severe acute respiratory syndrome coronavirus 2. "Altogether, these analyses point to a role for MAFB in shaping the transcriptome of pathogenic pulmonary macrophages in severe COVID-19." (PMID 37917179, 2023). "GSK3β inhibition prompts the acquisition of the transcriptional profile of severe COVID-19 pathogenic pulmonary macrophages via MAFB." (PMID 37917179, 2023). "The MAFB-dependent transcriptome of M-MØ is significantly overexpressed in pathogenic pulmonary macrophages from patients with severe COVID-19." (PMID 37917179, 2023). "As a whole, our results reveal a critical role of MAFB in shaping the transcriptome and functional ability of the monocyte-derived macrophage subsets that underlie the pathogenesis of pulmonary fibrosis in severe COVID-19." (PMID 37917179, 2023). "We have now assessed the role of MAFB in the response of monocyte-derived macrophages to SARS-CoV-2 through genetic and pharmacological approaches, and we demonstrate that MAFB regulated the expression of the genes that define pulmonary pathogenic macrophages in severe COVID-19." (PMID 37917179, 2023). "Although MAFB-dependent genes are enriched in severe COVID-19 pathogenic macrophages, the transcriptional changes observed in ΔMAFB M-MØ or CHIR-M-MØ could result from an indirect effect of MAFB silencing/overexpression." (PMID 37917179, 2023). "Given the overexpression of MAFB-dependent genes in severe COVID-19 pathogenic macrophages, we next assessed the effect of the pharmacological upregulation of MAFB (using the GSK3β inhibitor CHIR99021) on the gene sets that define pathogenic macrophages in severe COVID-19." (PMID 37917179, 2023). "Thus, pharmacological inhibition of GSK3β increases MAFB expression and reprograms macrophages toward enhanced expression of the gene signatures of macrophages associated to COVID-19 severity." (PMID 37917179, 2023). "As a whole, we propose that a high MAFB/MAF expression ratio in lung macrophages could serve as an accurate diagnostic tool for COVID-19 progression." (PMID 33312178, 2020). "Thus, MAFB determines the transcriptome and functions of the monocyte-derived macrophage subsets that underlie pulmonary pathogenesis in severe COVID-19 and controls the expression of potentially useful biomarkers for COVID-19 severity." (PMID 37917179, 2023). "As a whole, our findings demonstrate that MAFB significantly contributes to the acquisition of the gene profile and effector functions (cytokine/chemokine production) of the pathogenic macrophage subsets that promote pulmonary inflammation and fibrosis in severe COVID-19." (PMID 37917179, 2023). "A study on the transcriptomics of COVID-19 patients found MAFB to be significantly upregulated in the serum of patients who were placed in the intensive care unit." (PMID 40427565, 2025). "In this regard, since GSK3β inhibition potentiates the profibrotic phenotype in monocyte-derived macrophage through MAFB, the pharmacological modulation of the GSK3β/MAFB axis appears as a promising strategy for macrophage reprogramming in COVID-19." (PMID 37917179, 2023). "Altogether, analyses of monocyte-derived macrophages with altered MAFB expression (ΔMAFB M-MØ and MCTO M-MØ) fully support a role for MAFB in shaping the transcriptome of the pathogenic macrophage subsets in severe COVID-19." (PMID 37917179, 2023). "On the other hand, the possibility of altering the MAFB/MAF ratio as a potential therapy for severe COVID-19 raises the question of the appropriate timing for such an approach." (PMID 33312178, 2020). "The link between the MAFB/MAF ratio and the gene profile of pathogenic macrophages in severe COVID-19 has also mechanistic implications." (PMID 33312178, 2020). "In fact, Enrichr analysis on the COVID-19 gene sets supported the association between MAFB- and MAF-dependent genes and COVID-19." (PMID 33312178, 2020).